SDK2 (sidekick cell adhesion molecule 2)
Description:
Adhesion molecule that promotes lamina-specific synaptic connections in the retina and is specifically required for the formation of neuronal circuits that detect motion. Acts by promoting formation of synapses between two specific retinal cell types: the retinal ganglion cells W3B-RGCs and the excitatory amacrine cells VG3-ACs. Formation of synapses between these two cells plays a key role in detection of motion. Promotes synaptic connectivity via homophilic interactions.
Synonyms: KIAA1514; FLJ10832
Tractability: Antibody: its Gene Ontology location is reachable by antibodies, with high confidence; UniProt places it where antibodies can reach, with medium confidence; UniProt predicts a signal peptide or a membrane-spanning region. PROTAC: ubiquitination databases record sites on it; its protein half-life has been measured.
Gene: Protein-coding gene on chromosome 17 (73,334,384 to 73,644,445, reverse strand). Ensembl gene ENSG00000069188.
Subcellular location: Cell membrane; Synapse
Pathways (Reactome):
Cell-Cell communication: SDK interactions
Gene Ontology:
Molecular function: protein binding
Biological process: camera-type eye photoreceptor cell differentiation; homophilic cell-cell adhesion; retina layer formation; synapse assembly
Cellular component: plasma membrane; synapse
Genetic constraint (gnomAD): Loss-of-function variants: 101 observed, 214.94 expected, observed/expected ratio (o/e) 0.47, 90% interval 0.4 to 0.55. The upper end of that interval is the gene's LOEUF score, 0.55, which puts it in group 2 of 6, group 1 being the genes least tolerant of losing a copy. Missense variants: 2,567 observed, 2,828.6 expected, observed/expected ratio (o/e) 0.91, 90% interval 0.88 to 0.94. Synonymous variants: 1,232 observed, 1,148.1 expected, observed/expected ratio (o/e) 1.07, 90% interval 1.02 to 1.12.
Homologues: Orthologues: chimpanzee SDK2 (99% identical), macaque SDK2 (99% identical), dog SDK2 (96% identical), guinea pig SDK2 (96% identical), rat Sdk2 (95% identical), mouse Sdk2 (95% identical), rabbit SDK2 (88% identical), zebrafish sdk2b (81% identical), tropical clawed frog sdk2 (80% identical), zebrafish sdk2a (76% identical). Paralogues in human: SDK1 (59% identical), ROBO1 (13% identical), MXRA5 (13% identical), IGSF10 (13% identical), PTPRQ (13% identical), ROBO2 (13% identical), HMCN2 (12% identical), DCC (12% identical), NEO1 (12% identical), ROBO3 (12% identical), IGDCC4 (11% identical), DSCAM (11% identical), and 24 more.
Diseases named in the same sentence as SDK2 in open-access papers:
SDK2 is named in the same sentence as 3 diseases in open-access papers, as found by Europe PMC text mining. Sharing a sentence is not in itself a finding about the gene and the disease. The quoted sentences say what the papers report.
polymyositis (1 paper, 2023). A rare idiopathic inflammatory myopathy characterized by symmetric proximal muscle weakness and elevated muscle enzymes. "Four non‐HLA regions reached genome‐wide significance, SDK2 and LINC00924 (both novel) and STAT4 in the whole IIM cohort, with evidence of independent variants in STAT4, and NAB1 in the polymyositis (PM) subgroup." (PMID 36580032, 2023).
tumor (4 papers, 2008 to 2025). "Six loci (CLEC3B (previously TNA), MGP, RASSF1, SDK2, SERPINB5 and XAGE1A (previously GAGED2)) with statistically significantly higher methylation in tumor samples compared with non-tumor samples were identified." (PMID 18947422, 2008).
SDK2 also shares sentences with these, for which no sentence is quoted: panic disorder (1 paper).